CXCL1 (C-X-C motif chemokine ligand 1)
Diseases named in the same sentence as CXCL1 in open-access papers (continued):
Sharing a sentence is not in itself a finding about the gene and the disease.
steatosis (8 papers, 2020 to 2025). Increased lipid within the cytoplasm of cells. "Circulating levels of the chemokine GROα (CXCL1) were significantly increased in patients with NAFLD with cirrhosis compared to healthy controls or patients with simple steatosis." (PMID 38015590, 2023). "Interestingly, viral overexpression of CXCL1 in the liver is sufficient to trigger progression from steatosis to steatohepatitis in HFD-fed mice by inducing hepatic neutrophil infiltration, oxidative stress and hepatocyte apoptosis." (PMID 36980965, 2023). "Therefore, the inflammatory cytokines TNF-α, IL-1β, and IL-18 may combine with CXCL1 to synergistically induce liver injury and steatosis." (PMID 40606614, 2025). "Histological features were confirmed by real‐time PCR analyses, showing alcohol‐induced upregulation of the chemokines MCP‐1/CCL‐2 and CXCL1, along with the cytokine TNF‐α, implicated in hepatic inflammation, and of PPARγ that promotes both hepatic inflammation and steatosis." (PMID 39921321, 2025). "In the liver, this cytokine was reported to promote the progression from steatosis to non‐alcoholic steatohepatitis (NASH) by upregulating the expression of hepatocyte‐derived IL‐8 and chemokine CXCL1 to recruit neutrophils." (PMID 41026618, 2025).
colorectal tumor (7 papers, 2008 to 2024). "CXCL1 is highly expressed in human colorectal tumors, and both CXCL1 and CXCL2 are involved in IBD and believed to promote tumor angiogenesis by directly activating their shared receptor, CXCR2, on endothelial cells." (PMID 29720595, 2018). "However, there are also studies where the elevated CXCL1 expression in a colorectal tumor is inversely correlated with lymph node metastasis or tumor stage." (PMID 37408240, 2023). "Interestingly, both colorectal tumor tissues and hepatic metastatic tumor tissues showed apical and basal distribution of CXCL1 signals, whereas CRA tissues and unaffected corresponding neighbor tissues of CRC and CRA displayed only apical CXCL1 signals." (PMID 18578857, 2008). "Finally, CXCL1 expression in liver metastasis is lower than in the primary colorectal tumor." (PMID 37408240, 2023). "The level of colorectal tumor development cannot be definitely linked to the level of CXCL1 expression in the tumor, as some studies show a positive correlation and some a negative correlation between CXCL1 levels and colorectal tumor grade." (PMID 37408240, 2023). "Increased expression of CXCL-type chemokines, notably CXCL1, CXCL2, and CXCL8, was observed in colorectal tumor tissues." (PMID 38979413, 2024). "Tumour conditioned media obtained from cultured colorectal tumour explant tissue contained high levels of the chemokines CCL2, CXCL1, CXCL5 in addition to VEGF." (PMID 22125641, 2011).
esophageal cancer (7 papers, 2010 to 2023). A primary or metastatic malignant neoplasm involving the esophagus. "Similar correlations were observed in esophageal carcinoma, with CXCL1, CXCL2, CXCL3, and PPBP negatively correlated with EMT, CXCL5 and CXCL6 positively correlated with EMT, and CXCL8 not correlated with EMT." (PMID 37686093, 2023). "This signalling cascade was also shown to be involved in CXCL1 signalling in esophageal cancer and in CXCL8 secretion in primary human hepatocytes." (PMID 21044331, 2010). "The CXCL1/CXCR2 axis has been shown to participate in the regulation of ERK1/2 phosphorylation in esophageal cancer, which is responsible for the transcription of the EGR-1 gene, the crosstalk of among CXCL1/CXCR2 axis, ERK1/2 and EGR-1 result in a rapid increase in tumor cell proliferation." (PMID 35764974, 2022).
head and neck squamous cell carcinoma (7 papers, 2021 to 2025). A squamous cell carcinoma that arises from any of the following anatomic sites: lip and oral cavity, nasal cavity, paranasal sinuses, pharynx, larynx, and salivary glands. "Higher CXCL1 expression in the tumor is also associated with a worse prognosis of head and neck squamous cell carcinoma, including LSCC." (PMID 37408240, 2023). "Elevated CXCL1 levels in the blood of patients with head and neck cancer have been linked to radiation therapy failure, and higher CXCL1 expression in tumors is associated with a worse prognosis in head and neck squamous cell carcinoma." (PMID 40490643, 2025). "In head and neck squamous cell carcinoma tissues, CXCL1 can regulate the activation of fibroblasts and upregulate proinflammatory factors." (PMID 34976024, 2021). "Head and neck squamous cell carcinomas, including OSCC, are characterized by elevated CXCL1 expression compared to normal tissues." (PMID 40490643, 2025). "Head and neck squamous cell carcinoma, including oral squamous cell carcinoma (OSCC) and larynx squamous cell carcinoma (LSCC), show elevated CXCL1 expressions relative to healthy tissue." (PMID 37408240, 2023). "One case of a fusion gene, CXCL1-AFP, was detected in head and neck squamous cell carcinoma." (PMID 37686093, 2023).
heart failure (7 papers, 2019 to 2025). Inability of the heart to pump blood at an adequate rate to meet tissue metabolic requirements. "This shows that elevated levels of CXCL1 in the blood can lead to heart failure as shown by experiments on laboratory animals." (PMID 36613652, 2022). "Elevated blood levels of CXCL1 have been observed in patients with heart failure." (PMID 36613652, 2022). "Based on the inflammatory and fibrotic markers commonly observed in response to myocardial infarction and development of heart failure, we assessed the expression of mRNA for Tnfa, Il1b,Il6, Il18, Ccl2, Ccl3, Cxcl1, Cxcl2, Col1a1, Col3a1, Postn, and Tlr4 at 1 and 3 months." (PMID 35411847, 2022). "Patients with heart failure and chronic ischemic heart disease have elevated levels of CXCL1 in their blood, which indicates that increased, not decreased, blood levels of CXCL1 should be a marker of cardiotoxicity." (PMID 40427171, 2025).
malaria (7 papers, 2014 to 2025). Malaria is a serious and sometimes fatal disease caused by a parasite that commonly infects a certain type of mosquito which feeds on humans. "We observed increased IL-4, CXCL1, CXCL2, and CCL4 within the placenta, which have all been reported to be increased in humans, mice, or in vitro models of malaria (49, –, 52)." (PMID 40470930, 2025). "For cytokines IL-6, IL-1RA, IL-10 and IL-11 and chemokines CXCL1, CXCL8, CXCL10, CCL3 and CCL2, significantly higher concentrations were found in plasma samples of malaria patients compared to healthy controls." (PMID 34359826, 2021). "There was an associated increase in IL1-β (P = 0.03), IL-6 (P = 0.001), CXCL1 (P = 0.001) and MCP-1 (P = 0.003) serum levels in malaria-infected mice, when compared to the control group, on GD18.5." (PMID 31391498, 2019). "These genes include inflammatory responding genes, such as NFκB and CXCL1, parasite protein receptors, such as BSG and PROCR, and the genes involving protection against malaria, such as HLA-B and HAVCR1." (PMID 26099491, 2015). "Serum levels of IL1-β, IL-6, CXCL1 and MCP-1 were evaluated to determine whether gestational malaria induced a systemic inflammatory response." (PMID 31391498, 2019). "In addition to producing type I IFNs, DCs produce a wide range of pro-inflammatory cytokines, including TNF-α, IL-12, and IL-6, and chemokines, such as CXCL1, CXCL2, CCL2, CCL5, CXCL9, and CXCL10 in response to malaria parasites, and play crucial roles in malaria immunity and pathogenesis." (PMID 30619355, 2018).
myeloma (7 papers, 2014 to 2021). "Extracellular vesicles of multiple myeloma (MM) cells can stimulate secretion of cytokines, such as CXCL1, MCP1, IL6, IL-, IP-10, and CCL5 in mesenchymal stromal cells (MSCs) to promote MM cell growth and migration." (PMID 31024564, 2019). "When we added the inhibitor specific for ERK1/2, STAT1, STAT3, or Akt to cocultures of myeloma cells and MSCs, we found that the kinase inhibitor alone or in combination reduced the expression of CXCL1, CXCL2, SDF1, and MCP1 in myeloma cells." (PMID 34150666, 2021). "When we tested the putative angiogenic potential of the three chemokines, an increasing dose-response in the tubule formation assay was found for CXCL1 and CXCL5, even at lower concentrations than those required to induce myeloma growth." (PMID 25268740, 2014). "Serum concentrations of CXCL1 and CXCL5 in myeloma patients were below the concentrations used in our in vitro studies (186.5 ± 129.1 pg/ml and 765 572.1 pg/ml, respectively)." (PMID 25268740, 2014). "In addition, we found that direct co-culture of hMSCs with two myeloma cell lines prior to and during adipogenic differentiation resulted in increased secretion of CXCL1/GRO, IL-8, and ICAM-1 in co-culture conditioned medium samples." (PMID 33680918, 2020).
ovarian tumor (7 papers, 2016 to 2025). "The pre-spreading of ovarian tumors shows the expression of CXCL1 and other CXCR2 ligands as well as the expression of CXCR4." (PMID 37108425, 2023). "The level of CXCL1 expression in ovarian tumors differentially affects the prognosis for patients, according to the cited work." (PMID 37108425, 2023). "A similar trend was observed for cytokines TNF-α and CXCL1 when A2780 ovarian tumor cells were selected for docetaxel resistance." (PMID 28915246, 2017). "MSC may also be responsible for CXCL1 expression in ovarian tumors." (PMID 37108425, 2023). "Nevertheless, CXCL1 may be important only in the early stages of ovarian tumor development." (PMID 37108425, 2023).
renal fibrosis (7 papers, 2021 to 2025). A final common manifestation of a wide variety of chronic kidney diseases characterized by glomerulosclerosis and tubulointerstitial fibrosis. "In our study, Ang II infusion markedly increased the levels of chemokines (CXCL1 and GCSF) and CXCR2 (the receptor of CXCL1) in the kidney, and Dectin-1 deficiency attenuated Ang II-induced renal dysfunction and renal fibrosis." (PMID 37340199, 2023). "Recent studies have indicated that damaged PT cells release CXCL1, which attracts immune cells and promotes the progression of renal fibrosis." (PMID 39691368, 2024). "In short, COL4A2, CXCL1, TIMP1, VCAM1, and VEGFA are promising diagnostic biomarkers of tissue and serum for renal fibrosis, which is helpful for the early diagnosis and treatment of patients with renal fibrosis." (PMID 37266443, 2023). "COL4A2, CXCL1, TIMP1, VCAM1, and VEGFA are promising diagnostic biomarkers of tissue and serum for renal fibrosis." (PMID 37266443, 2023). "A single-cell analysis pointed out that CXCL1 is secreted from pro-fibrotic tubules and then recruits CXCR2 + basophils, which is a key factor in renal fibrosis." (PMID 40078458, 2025). "COL4A2, CXCL1, TIMP1, and VCAM1 have all been shown to be elevated in renal fibrosis, which is consistent with the findings of our experimental study." (PMID 37266443, 2023). "Five genes (COL4A2, CXCL1, TIMP1, VCAM1, and VEGFA) were subsequently identified as biomarkers for renal fibrosis through machine learning, and their expression levels were confirmed by validation cohort data sets and in vitro RT-qPCR experiment." (PMID 37266443, 2023). "In addition, the elevated secretion of pro-inflammatory cytokines, including M1-related CXCL1 and CXCL10 and M2-related CCL17 and CCL26, may augment in the early phase of renal inflammation and in the late phase of renal fibrosis in folic acid-induced RIF." (PMID 35990680, 2022).
skin cancer (7 papers, 2009 to 2024). "CXCL1 also plays an important role in inflammatory responses in the skin and contributes to the development of skin tumours." (PMID 39533922, 2024). "CXCL1 is strongly and highly differentially expressed in primary and metastatic melanoma and in other skin cancers." (PMID 20030852, 2009). "Besides gastric, colon and skin cancers, up-regulated CXCL1 has been reported in many different types of kidney diseases." (PMID 25816025, 2015).
skin infection (7 papers, 2020 to 2025). An inflammatory process affecting the skin, caused by bacteria, viruses, parasites, or fungi. "Although CXCL1 and neutrophils have been previously implicated in C. albicans infection, their involvement in the skin infection of C. albicans was unclear." (PMID 32093731, 2020). "Previous studies have demonstrated that GSDMD mitigates S. aureus skin infections by suppressing Cxcl1-Cxcr2 signaling and plays a critical role in protecting skin tissues during infection." (PMID 41305370, 2025). "More importantly, inhibiting the Cxcl1–Cxcr2 axis with a Cxcr2 inhibitor or anti-Cxcl1 blocking antibody rescued defects in host defence against S. aureus skin infection in the GSDMD−/− mice." (PMID 34011393, 2021). "Collectively, these results showed that the Cxcl1–Cxcr2 axis is responsible for the decreased host defence against S. aureus skin infection in the GSDMD−/− mice." (PMID 34011393, 2021). "Neutrophils play an essential role in targeting and eliminating S. aureus during a skin infection, while keratinocytes are able to secrete CXCL1 and CXCL8, which are the primary chemokines responsible for neutrophil recruitment and stimulation of neutrophil degranulation." (PMID 35804301, 2022). "Next, we evaluated whether inhibiting the Cxcl1–Cxcr2 axis in the GSDMD−/− mice could rescue impaired host defence against S. aureus skin infection." (PMID 34011393, 2021). "We adopted a well-known mouse model of skin infection to look at the expression of pro-inflammatory genes TNF and CXCL1 and the transcriptional factors NF-κB and IRF3 after the treatment with poly I:C or the vehicle." (PMID 32824595, 2020). "The local CXCL1 and CXCL2 synthesis decrease with age, thus promoting infection spread in a mouse model of soft-tissue and skin infection." (PMID 31936467, 2020). "Corroborating in vitro data, Myd88−/− knockout mice downregulated TNF, CXCL1; and phospho-p65 and phospho-IRF3 nuclear localization, upon poly I:C treatment in a mouse model of skin infection." (PMID 32824595, 2020). "Our data show that iKIR enhances specifically the production of pro-inflammatory cytokines known to drive proper abscess formation and improved infection outcome (IL-1β), neutrophil recruitment (CXCL1 and CXCL2), but not monocyte recruitment (CCL2) in response to MRSA skin infection." (PMID 33690673, 2021).
skin inflammation (7 papers, 2016 to 2024). "Compared with WT mice, KO mice showed an increased susceptibility to P. acnes-induced skin inflammation, as evidenced by higher levels of pro-inflammatory factors such as Cxcl1, Il-1α, Il-1β, Il-6 and Tnf-α in the knockout mice." (PMID 35414779, 2022). "Compared with normal mice, jet-lagged mice were more sensitive to P. acnes-induced skin inflammation, as evidenced by higher levels of pro-inflammatory factors such as Cxcl1, Il-1α, Il-1β, Il-6 and Tnf-α." (PMID 35414779, 2022). "Compared with wild-type mice, Rev-erbα-/- mice showed an increased sensitivity to P. acnes-induced skin inflammation, as evidenced by higher levels of pro-inflammatory factors such as Cxcl1, Il-1α, Il-1β, Il-6 and Tnf-α in the knockout mice." (PMID 35414779, 2022). "Previous research has indicated that alpha-toxin phenol-soluble modulins (PSMs) secreted by Staphylococcus aureus can significantly induce the expression of pro-inflammatory chemokines such as Cxcl1 and Cxcl3 in human primary keratinocytes, exacerbating skin inflammation." (PMID 39684557, 2024). "The HFD- or propionate-induced reduction in CXCL1/2 or CCL20 expression might result in the reduced infiltration of neutrophils or T cells/γδT cells in the imiquimod-induced dermatitis, respectively." (PMID 37762500, 2023). "In imiquimod-induced dermatitis, IL-17A, IL-17F, and IL-22 may be mostly derived from Th17 cells or γδT17 cells, while CXCL1, CXCL2, CCL20, and IL-17C may be mainly produced by epidermal keratinocytes." (PMID 37762500, 2023). "Oral propionate decreased mRNA expression of IL-17A, IL-17C, IL-17F, IL-22, IL-6, IL-1β, TNF-α, CXCL1, and CCL20 in imiquimod-induced dermatitis in comparison between NDIS versus NDIP." (PMID 37762500, 2023). "Oral propionate reduced inflammatory infiltrates and epidermal Ki67+ cells and reduced mRNA levels of IL-17A, IL-17F, IL-17C, IL-22, IL-1β, IL-6, TNF-α, CXCL1, CCL20 and increased those of TGF-β1and IL-10 in imiquimod-indued dermatitis." (PMID 37762500, 2023). "The HFD decreased mRNA expression of IL-17A, IL-17F, IL-22, TNF-α, IL-1β, CXCL1, CXCL2, and keratin 16, and increased mRNA expression of TGF-β1 and CDKN1A in imiquimod-induced dermatitis." (PMID 37762500, 2023). "HFD reduced mRNA levels of IL-17A, IL-17F, IL-22, IL-1β, tumor necrosis factor (TNF)-α, CXCL1, CXCL2, and keratin 16 and increased those of transforming growth factor (TGF)-β1 and cyclin-dependent kinase inhibitor 1A in imiquimod-induced dermatitis." (PMID 37762500, 2023). "Oral propionate and the HFD reduced mRNA expression of IL-17A, IL-17C, IL-17F, IL-22, IL-1β, IL-6, TNF-α, CXCL1, CXCL2, and CCL20 in imiquimod-induced dermatitis." (PMID 37762500, 2023).
type 2 diabetes (7 papers, 2012 to 2025). "Immunomodulatory molecules CXCL1 and IL-12p40 have been linked to type 2 diabetes and other inflammatory diseases." (PMID 39940428, 2025). "Among them, Cxcl1 and Cxcl5 have been found to be altered in the serum of patients with type 2 diabetes." (PMID 25073444, 2014). "Moreover, CXCL1/GRO-α and IL-8 also exhibited higher expression in the adipose tissue of obese subjects as well as in the circulation of obese mice and humans in association with insulin resistance and type 2 diabetes." (PMID 37509065, 2023).
abscess (6 papers, 2013 to 2024). An inflammatory process characterized by the accumulation of pus within a newly formed tissue cavity which is the result of a bacterial, fungal, or parasitic infection or the presence of a foreign body. "Unexpectedly, we found a rim of live hepatocytes expressing Cxcl1 surrounding the abscesses by 5 dpi." (PMID 38096412, 2023). "Analyzing the specific functions of these cells, and how their roles in abscess formation and resolution is regulated by Cxcl1, should be experimentally approachable using CRISPR-based technology to genetically modify hepatocytes in vivo." (PMID 38096412, 2023). "After this normalization, CXCL1 and IL-17 were significantly decreased during biofilm infection compared to planktonic abscesses (respectively)." (PMID 24386336, 2013). "histolytica infection, abscess volume and the percentage of Ly6Chi cells among the total Ly6C+ monocyte population in the liver were reduced to a greater extent by the CXCL1-depleting antibody than by the isotype control." (PMID 32651360, 2020). "More interesting was the observation that genetic deletion of either C5aR1 or C5aR2 resulted in enhanced production of neutrophil chemoattractant CXCL1 and in the infiltration of neutrophils into the infected kidneys, accelerated abscess formation and increased tissue damage." (PMID 26512700, 2015). "Since the impact of CXCL1 on abscess development had not been investigated until now, it was of crucial importance to analyze the role of this chemokine during E. histolytica infection." (PMID 32651360, 2020).